TMEM63B (transmembrane protein 63B)
Description:
Mechanosensitive cation channel with low conductance and high activation threshold. Osmosensitive cation channel preferentially activated by hypotonic stress. Also acts as a phospholipid scramblase in response to changes in membrane structure: upon changes in membrane curvature and thickness, alters its conformation and translocates phospholipids, such as phosphatidylcholine and sphingomyelin, thereby controlling plasma membrane lipid distribution. Forms a heterodimer with SLC19A2, which mediates phospholipid scramblase activity following Ca(2+) stimulation (By similarity). Expressed in excitatory neurons of the subfornical organ and functions as a thirst receptor that mediates neuronal response to hyperosmolality to drive thirst and drinking behavior (By similarity). Facilitates intestinal motility by promoting proliferation of intestinal stem cells (By similarity). Essential for the baby's first breath and respiration throughout life. Upon lung inflation conducts cation currents in alveolar type 1 and 2 cells triggering lamellar body exocytosis and surfactant secretion into airspace. Acts as an osmosensor in cochlear outer hair cells (OHCs) where it mediates calcium influx and regulatory volume decrease response (By similarity). Required for the maintenance of OHC morphology, OHC survival and normal hearing (By similarity).
Synonyms: hTMEM63B; C6orf110; DKFZp434P0531; dJ421H19.2; DEE118
Tractability: Antibody: UniProt places it where antibodies can reach, with high confidence; its Gene Ontology location is reachable by antibodies, with high confidence; UniProt predicts a signal peptide or a membrane-spanning region; the Human Protein Atlas places it where antibodies can reach. PROTAC: ubiquitination databases record sites on it; its protein half-life has been measured.
Gene: Protein-coding gene on chromosome 6 (44,126,614 to 44,155,520, forward strand). Ensembl gene ENSG00000137216.
Subcellular location: Cell membrane; Endoplasmic reticulum membrane; Lysosome membrane; Early endosome membrane
Subcellular location (Human Protein Atlas): Actin filaments; Plasma membrane
Gene Ontology:
Molecular function: calcium-activated cation channel activity; mechanosensitive monoatomic cation channel activity; mechanosensitive monoatomic ion channel activity; phospholipid scramblase activity; osmolarity-sensing monoatomic cation channel activity; phosphatidylcholine transfer activity; sphingomyelin transfer activity
Biological process: drinking behavior; intestinal stem cell homeostasis; sensory perception of sound; surfactant secretion; monoatomic cation transmembrane transport; monoatomic ion transmembrane transport; phospholipid transport; plasma membrane phospholipid scrambling
Cellular component: actin cytoskeleton; alveolar lamellar body membrane; early endosome membrane; lysosomal membrane; plasma membrane; endoplasmic reticulum membrane; membrane
Genetic constraint (gnomAD): Loss-of-function variants: 23 observed, 103.81 expected, observed/expected ratio (o/e) 0.22, 90% interval 0.16 to 0.31. The upper end of that interval is the gene's LOEUF score, 0.31, which puts it in group 1 of 6, group 1 being the genes least tolerant of losing a copy. Missense variants: 628 observed, 1,134.5 expected, observed/expected ratio (o/e) 0.55, 90% interval 0.52 to 0.59. Synonymous variants: 444 observed, 457.71 expected, observed/expected ratio (o/e) 0.97, 90% interval 0.9 to 1.05.
Homologues: Orthologues: chimpanzee TMEM63B (100% identical), dog TMEM63B (99% identical), guinea pig TMEM63B (99% identical), mouse Tmem63b (98% identical), rat Tmem63b (98% identical), pig TMEM63B (97% identical), rabbit TMEM63B (92% identical), tropical clawed frog tmem63b (85% identical), macaque TMEM63B (80% identical), zebrafish tmem63ba (77% identical), zebrafish tmem63bb (15% identical), zebrafish zgc:153431 (8% identical). Paralogues in human: TMEM63A (53% identical), TMEM63C (41% identical).
Diseases named in the same sentence as TMEM63B in open-access papers:
TMEM63B is named in the same sentence as 16 diseases in open-access papers, as found by Europe PMC text mining. Sharing a sentence is not in itself a finding about the gene and the disease. The quoted sentences say what the papers report.
colitis (1 paper, 2024). Inflammation of the colon. "To assess the impact of TMEM63B on ISC proliferation, we treated mice with DSS (a colitis model) and found that TMEM63B cKO mice exhibited more severe colitis symptoms compared to controls, including significant body weight loss and shorter colon length." (PMID 39513891, 2024). "In the colitis model, the TMEM63B deletion in ISC mice exhibited a more severe intestinal injury, indicating that the deletion of TMEM63B impaired the reparative capacity of intestinal epithelial cells." (PMID 39513891, 2024). "However, the conditional knockout (cKO) of TMEM63B specifically in ISCs prevented the rapid proliferation and repair of a damaged epithelium when colitis occurred, ultimately leading to more severe colitis symptoms." (PMID 39513891, 2024). "The deletion of TMEM63B in intestinal stem cells not only decelerates intestinal motility and impairs digestion but also attenuates the proliferation of intestinal stem cells and exacerbates DSS-induced colitis in mice." (PMID 39513891, 2024).
developmental and epileptic encephalopathy (1 paper, 2025). An epilepsy associated with developmental impairment that may be due to either the underlying etiology or the superimposed epileptic activity, or both. "Variants in HCN1 and TMEM63B have been linked to developmental and epileptic encephalopathy (DEE)." (PMID 40167904, 2025).
diabetes (1 paper, 2020). "The effects of diabetes were partly mediated by the altered methylation of HOOK2, LCE3C, and TMEM63B." (PMID 32075680, 2020).
epileptic encephalopathies (1 paper, 2025). "Recently, heterozygous mutations of TMEM63b have been identified in patients with severe early-onset developmental and epileptic encephalopathies and progressive neurodegeneration." (PMID 39707024, 2025).
hearing loss (1 paper, 2022). "Other genes were related to BPD-associated outcomes such as retinopathy of prematurity (ROP, e.g., GBP3, FJX1, HIPK2) and hearing loss (e.g., GJB6, TMEM63B) and mitochondrial energy metabolism (e.g., TOMM7, SLC25A26, SLC25A33, PDK1, PKM, MDH1)." (PMID 35484630, 2022).
Intellectual disability (1 paper, 2020). "One de novo variant in TMEM63B was observed in three DDD and 100KGP patients with consistent intellectual disability, movement and brain morphology phenotypes that were recapitulated in the IMPC Tmem63b mutant mouse." (PMID 32005800, 2020).
lung carcinoma (1 paper, 2021). "Three genes, TFAP2A, TJP1 and TMEM63B, have been shown to be associated with the B lymphocytes in lymph node metastasis of lung cancer." (PMID 34575089, 2021). "As for TMEM63B, it has also been shown to be associated with immune responses during the metastasis of lung cancer, associated with the summarized cell subtype." (PMID 34575089, 2021).
overactive bladder (1 paper, 2025). Symptom of overactive detrusor muscle of the urinary bladder that contracts with abnormally high frequency and urgency. "We also assessed whether the overactive bladder phenotype that results from treatment with CYP would be affected by loss of Tmem63b expression." (PMID 41348674, 2025).
respiratory failure (1 paper, 2024). The significant impairment of gas exchange within the lungs resulting in hypoxia, hypercarbia, or both, to the extent that organ tissue perfusion is severely compromised. "Here, we show that loss of the mechanosensitive channels TMEM63A and TMEM63B (TMEM63A/B) resulted in atelectasis and respiratory failure in mice due to a deficit of surfactant secretion." (PMID 38127458, 2024).
bacterial infections (1 paper, 2025). "Thus, by altering urine composition (e.g., making it hypertonic or hypotonic) or by exposing the bladder to bacterial infections, or chronic disease states such as partial outlet obstruction or spinal cord injury, we may reveal a role for Tmem63b." (PMID 41348674, 2025).
TMEM63B also shares sentences with these, for which no sentence is quoted: cancer (1 paper); ductal carcinoma (1); lymph node metastasis (1); melanoma (1); retinopathy of prematurity (1); tumor (1).